HTR2C (5-hydroxytryptamine receptor 2C)
Diseases named in the same sentence as HTR2C in open-access papers (continued):
Sharing a sentence is not in itself a finding about the gene and the disease.
Constipation (1 paper, 2021). Infrequent or difficult evacuation of feces. "Three genes, 5-HT receptor subtype 2a and 2c (Htr2a and Htr2c) and Transient receptor potential vanilloid 2 (Trpv2) were significantly upregulated in the constipation group in comparison to the control group." (PMID 33441874, 2021). "A significant upregulation of serotonin receptors, Htr2a and Htr2c, was observed in the bladders from mice with constipation, paralleled with augmented spontaneous contractions after pre-incubation of the bladder strips with 0.5 μM of serotonin." (PMID 33441874, 2021).
female infertility (1 paper, 2023). Diminished or absent ability of a female to achieve conception. "Based on previous published studies, we speculated that other three genes (UBQLN1, HTR2C, and ZFPM2) may also play a role in female infertility besides TUBA4A." (PMID 37024973, 2023).
glioma (1 paper, 2023). A benign or malignant brain and spinal cord tumor that arises from glial cells (astrocytes, oligodendrocytes, ependymal cells). "In high-grade gliomas, RYR2, MCHR2, FADS6, HTR2C, CMTM3, APH1A, and PFN1 genes are related to membrane function." (PMID 37239411, 2023).
Headache (1 paper, 2022). Cephalgia, or pain sensed in various parts of the head, not confined to the area of distribution of any nerve. "The expression of 5‐HT receptor genes, Htr1a, Htr1f, and Htr2c, was found to be activated in this study and contributed to headaches and behavioral inhibition in mice." (PMID 36514756, 2022).
infertile (1 paper, 2023). "We found 4 genes (TUBA4A, UBQLN1, HTR2C, and ZFPM2) with at least two damaging DNMs in infertile females and these 4 genes were significantly enriched in our affected individuals compared to other control groups." (PMID 37024973, 2023).
invasive lobular breast carcinoma (1 paper, 2023). An infiltrating lobular adenocarcinoma of the breast. "HTR2C was found highly expressed in invasive lobular breast carcinoma with a FC of 2.517 (Turashvili Breast Statistics) and decreased in male breast carcinoma with a FC of 2.041 (TCGA breast statistics)." (PMID 37795441, 2023).
leukemia (1 paper, 2024). A malignant (clonal) hematologic disorder, involving hematopoietic stem cells and characterized by the presence of primitive or atypical myeloid or lymphoid cells in the bone marrow and the blood. "We first analysed the DA1-3b leukemia model and among the 70 commonly mutated genes in dormant leukemia DA1-3b/D365 and parental DA1-3b cells, ten genes (Ttc7b, Dnmt3b, Ap1b1, Ne1, Nedd4, Acy1, Cyp11a1, Htr2c, Magee1 and Gdi1) were amplified in dormant and parental cells." (PMID 39223638, 2024).
melanoma (1 paper, 2023). A malignant, usually aggressive tumor composed of atypical, neoplastic melanocytes. "5-NL’s affinity for other receptors including HTR1A-B and HTR2C broadens the range of targets since human melanoma cells do express other HTR’s as do murine B16 and MC-38 cells." (PMID 37582744, 2023).
non-small cell lung carcinoma (1 paper, 2021). A group of at least three distinct histological types of lung cancer, including non-small cell squamous cell carcinoma, adenocarcinoma, and large cell carcinoma. "HTR2C was found to be involved in the non-small-cell lung cancer pathway, directly affecting epidermal growth factor receptor tyrosine kinase inhibitor resistance." (PMID 33968297, 2021).
respiratory depression (1 paper, 2022). A decrease in ventilation secondary to impaired signals from the central nervous system. "Also, we do not yet know the ontological relationships of PB neurons expressing Oxtr1 (water intake), Htr2c (food, water, and salt intake), or Oprm1 (opioid‐withdrawal; opioid‐induced respiratory depression) relative to our developmental‐genetic framework." (PMID 35134251, 2022).
tumor (5 papers, 2021 to 2025). "Among these 5-HTRs, HTR7, HTR2A, HTR2B, and HTR2C were extensively studied in different tumor tissues." (PMID 37795441, 2023). "The calcium signaling pathway (hsa04020) contained 23 genes (p = 8.81 × 10−7), including key receptors such as SLC8A2, HTR2C, GRIN1, CACNA1I, and GRIN2B, which regulate intracellular calcium levels and tumor microenvironment dynamics via glutamate interactions." (PMID 40406701, 2025). "However, 5-NL also has affinity for other HTR receptors also expressed by tumor cells in our system namely HTR1A-B, HTR2A and HTR2C." (PMID 37582744, 2023). "At the molecular level, our bioinformatics analysis results suggested that HTR2C, TACR3, MCHR2 and GHSR might be LINC01296 targets through tumor microenvironment and phosphorylation regulation." (PMID 34515611, 2021).
movement disorder (2 papers, 2012 to 2020). Neurological conditions resulting in abnormal voluntary or involuntary movement, which may impact the speed, fluency, quality and ease of movement. "In a population with chronic mental illness, various tag SNPs in 7 candidate genes (GRIN2B, GRIN2A, HSPG2, DRD3, DRD4, HTR2C, and NQO1) reached nominally significant (p≤0.05) associations with drug-induced movement disorders." (PMID 23226551, 2012). "HTR2C could also have a role in the pathogenesis (related to its incidence) of this movement disorder, but this cannot be estimated." (PMID 32390801, 2020).
brain diseases (1 paper, 2016). "These included Ihh (Indian hedgehog; CvN), related to “cell–cell adhesion” and “brain diseases”, Hrh2 (histamine receptor H2; CvA), and Htr2c (serotonin receptor 2C; CvI), both related to important categories of GO processes and diseases." (PMID 27782041, 2016).
HTR2C also shares sentences with these, for which no sentence is quoted: cancer (6 papers); diabetes (3); Dyskinesia (3); anxiety disorder (2); cognitive deficits (2); Huntington disease (2); hyperprolactinemia (2); Impaired glucose tolerance (2); mood disorder (2); neurological diseases (2); Prader-Willi syndrome (2); psychosis (2); Seizure (2); Tinnitus (2); type 2 diabetes (2); Anorexia (1); attention deficit-hyperactivity disorder (1); bulimia (1); Cachexia (1); cardiac hypertrophy (1); Cerebral ischemia (1); choroid plexus tumors (1); cocaine addiction (1); colorectal cancer (1); deficiencies (1); Dravet syndrome (1); Dystonia (1); eating disorder (1); embryonic carcinoma (1); emotional dysregulation (1).
A further 30 diseases each share a sentence with HTR2C in 1 paper.